STAT3 (signal transducer and activator of transcription 3)
Diseases named in the same sentence as STAT3 in open-access papers (continued):
Sharing a sentence is not in itself a finding about the gene and the disease.
cancer (continued). "The FM@PFC/siRNA nanoemulsions effectively inhibit STAT3 and CXCR4 signaling pathways, leading to increased apoptosis and reduced cancer cell invasion." (PMID 40166646, 2025). "TIAM1 promotes cancer cell proliferation, invasion, and metastasis via multiple pathways, including AKT/mTOR signaling and ERK/STAT3 signaling." (PMID 40228435, 2025). "RBP4 activates STRA6, leading to activation of Janus kinase and STAT3/STAT5, which results in pro-inflammatory response and tumorogenesis.This results in cancer progression, migrations, and metastasis." (PMID 41007818, 2025). "Furthermore, signaling pathways mediated by hyperactivated STAT3 can promote the formation, stemness, and self-renewal of BCSCs by enhancing fatty acid oxidation, while also driving uncontrolled cell proliferation and survival, thereby fostering chemoresistance in cancer cells." (PMID 40949156, 2025). "Stat3, Akt and ERK1/2 are signaling molecules in the downstream three main signal pathways of the EGFR, which is abnormally activated in various cancer cells." (PMID 40076615, 2025). "The expression of PD-L1 in different cancers can be regulated by a number of transcriptional factors, including HIF-1, STAT3, NF-κΒ, and AP-1 and certain oncogenic pathways such as JAK/STAT, RAS/ERK, or PI3K/AKT/MTOR." (PMID 40149335, 2025). "Specifically, LDHB was shown to be positively regulated by the RTK–PI3K–AKT–mTOR signaling axis and stimulated by signal transducer and activator of transcription 3 (STAT3), a key tumorigenic driver across numerous cancers." (PMID 40733189, 2025). "Further research has associated HPA and SNS dysregulation with various pro-tumoral pathways in cancer cells, including JAK/STAT3, MAPK, PI3K/Akt, WNT/β-catenin, NFκB, and immune system modulation." (PMID 41488655, 2025). "Chronic inflammation activates the transcription of nuclear factor kappa-light-chain-enhancer of activated B (NF-kB), STAT3, and activator protein 1 (AP1), which, cooperatively with hypoxia, promote cancer cell growth and angiogenesis." (PMID 40507982, 2025). "CUR analogues, such as L48H37 and compound 5 k, have shown promise in inhibiting cancer cell motility, migration, and invasion by modulating the JAK/STAT and NF‐κB/STAT3 signaling pathways." (PMID 40860906, 2025). "The overexpression of STAT3, or the re-expression of NANOG, has been observed in a variety of cancer cells." (PMID 40729003, 2025). "Meanwhile, lncRNAs mainly focused on binding proteins such as STAT3 and CTCF, as well as cancer features such as invasion, metastasis, and epithelial–mesenchymal transition." (PMID 40444278, 2025). "Paired qPCR results comparing cancer and adjacent tissues indicated elevated mRNA expression of IL6, JAK and STAT3 in cancer tissues, along with an increase in the activity of the IL6‐JAK‐STAT3 pathway, compared to adjacent tissues." (PMID 39893643, 2025). "Given STAT3’s established role in modulating glucose metabolism, this regulation suggests a direct link between STAT3 and TKT in cancer cell metabolism reprogramming." (PMID 40230848, 2025). "Using genomic and proteomic data in DEPMAP database, we found that the expression of TXNRD1 and STAT3 genes and mTOR pS2448 protein were higher in CDDP resistance cancer cells compared to sensitive cancer cells to CDDP." (PMID 39859517, 2025). "The cancer cells of NPC patients showed high levels of EGFR and phosphorylated STAT3, indicating that a STAT3-dependent pathway is crucial for NPC development." (PMID 40244228, 2025). "We propose a mechanistic model in which dual targeting of CAV1 and AXL impairs the pro-survival signalling via STAT3, AMPKα, and RAC pathways, thereby promoting excessive autophagy and inducing cancer cell death to overcome TKI resistance in HCC." (PMID 40715090, 2025). "In cancer cachexia, components of the UPS are activated by the inflammatory cytokines TNF-α and IL-6 via the NF-κB and STAT3 pathways, which upregulate MuRF1 and atrogin-1 expression." (PMID 40869331, 2025).
cancer (continued). "By triggering the formation of a ternary complex involving STAT3, D-PROTAC, and the E3 ligases VHL, STAT3 undergoes efficient degradation in cancer cells via a mechanism reliant on both the E3 ligases VHL and the proteasome." (PMID 40118821, 2025). "The constitutive activation of signal transducer and activator of transcription 3 (STAT3) has been identified as a significant contributor to oncogenesis, with activated STAT proteins observed across various human cancers." (PMID 40149421, 2025). "The release of MCP1 by IL-6 signaling in human vascular endothelial cells induces the activation of the JAK/STAT3 and PI3K/AKT pathways, also in various cancer cells." (PMID 40430040, 2025). "By decreasing IL-6, STAT3, NF-κB, PGE-2, COX-2, and TNF-α levels, combining the effects of prebiotics and probiotics helps lower inflammation and inhibit cancer-promoting pathways, offering a promising strategy for CRC prevention and treatment." (PMID 41322104, 2025). "Evidence has highlighted lysine acetylation as an additional modulatory mechanism that can control STAT3 protein activity and the CSC-like properties of various cancers." (PMID 40083697, 2025). "Among these, the STAT3, Akt, and ERK pathways play critical roles in cancer cell proliferation, survival, and angiogenesis and are often associated with poor prognosis and drug resistance." (PMID 39558814, 2025). "Based on this analysis, the genes STAT3, MYC, CTNNB1, ESR1, JUN, and BRCA1 emerged as pivotal genes, indicating their significant impact on each cancer type in response to radiation exposure." (PMID 41186627, 2025). "Actually, kinds of JAK/STAT inhibitors have been examined for their clinical significance in diverse cancers, including HCC, mainly focused on JAK and STAT3 inhibitors." (PMID 39915447, 2025). "Specifically, STAT3 phosphorylation has been found to increase DNMT1, DNMT3A, and DNMT3B expression in cancer cells." (PMID 40427627, 2025). "Protein–protein interaction networks identified hub genes for each cancer type, with key shared targets including EGFR, ESR1, PTGS2, and STAT3." (PMID 41155677, 2025). "Neutrophils also activate lipid carrier protein 2 (LCN2) secretion through enhanced STAT3 and induce mesenchymal–epithelial transition (MET) in cancer cells, acquiring an invasive phenotype, thereby promoting cancer cell colonization and metastasis." (PMID 40979214, 2025). "HER3 expression levels were substantially higher in resistant cancer tissues and cells, and HER3 was the upstream facilitator of suppressing CYLD expression via STAT3 signaling." (PMID 40012003, 2025). "Various transcription factors can upregulate CD47 on the surface of cancer cells, such as MYC, nuclear factor kappa B (NFκB), signal transducer and activators of transcription 3 (STAT3), and hypoxia-inducible factor-1(HIF-1)." (PMID 40835598, 2025). "CPA4’s role in cancer has been attributed to its disruption of many cellular signaling pathways, e.g., PI3K-AKT-mTOR, STAT3-ERK, AKT-cMyc, GPCR, and estrogen signaling." (PMID 40805261, 2025). "Inflammatory factors (IL-6, STAT3, YAP1, NF-κB, COX-2/PGE2, and NO) induce stemness, which promotes cancer progression." (PMID 40244228, 2025). "The JAK2/STAT3 and ERK pathways are well known for their roles in regulating cell proliferation, survival, migration, and invasion in various cancers." (PMID 40075566, 2025). "STAT3 activity in CAFs induces the release of IL-6, TGF-β, and VEGF by cancer cells, promoting immunosuppression and metastasis)." (PMID 40136652, 2025). "In cancer cells, low level of ECA induces DNA damage and the following activation of NFκB and STAT3, which sustains proliferation and stemness." (PMID 40875771, 2025). "In bladder cancer, the PI3K/Akt/STAT3 signaling pathway, which induces MMP-2 and MMP-9 expression, is crucial for enhancing the migration and invasion of cancer cells promoted by B7-H3." (PMID 40214484, 2025).
cancer (continued). "Another important regulatory factor is STAT3, which has been shown to modulate B7-H3 expression through the JAK/STAT signaling pathway, particularly in cancers with high STAT3 activity." (PMID 40230524, 2025). "STAT3 also regulates transcription factors Sox2 and NANOG, which contribute to cancer cell stemness, and TWIST1 and Vimentin, which promote the epithelial–mesenchymal (EMT) transition to occur." (PMID 40075607, 2025). "In contrast, the CUR pre-treatment represents a promising alternative method of therapy designed to boost the CDDP effect specifically ovarian CDDP- resistance SKOV-3/CDDP cancer cell line through induction apoptosis by down-regulating TRXR1, mTOR/STAT3." (PMID 39859517, 2025). "The induction of oxidative stress has also been observed with other anti-cancer agents targeting the PI3K/AKT/mTOR, MEK/ERK, and STAT3 signaling axes, although effects differ between model systems." (PMID 40563571, 2025). "We studied their influence on the expression of STAT3 and NANOG, which play a confirmed role in different stages of cancer development." (PMID 40729003, 2025). "Previous studies have demonstrated that chemotherapy activates NF-κB via the AKT-IκB pathway and STAT3 via the IL-6R/JAK1 pathway, leading to PD-L1 expression and contributing to chemotherapy resistance in cancer cells." (PMID 40999385, 2025). "EA has also been demonstrated to inhibit the activation of key signaling kinases, such as the phosphorylated form of STAT3, Akt kinase, and ERK1/2, thereby leading to the inhibition of the PI3K/Akt/mTOR pathway, which is often overactive in cancer cells." (PMID 40572559, 2025). "IL-8, produced during co-culture, activated STAT3 in macrophages, which in turn enhanced the stemness of SKOV3 cells by increasing their ability to form spheres and colonies, and by upregulating cancer stem cell markers CD133 and CD44." (PMID 40330466, 2025). "In summary, our study highlights the epigenetic impact of STAT3 acetylation on DIRAS2 expression and reveals a potential feedback loop involving TAMs and cancer cells." (PMID 40083697, 2025). "Collectively, these axes (hepcidin–STAT3–HIF-2α) link elevated iron status to hypoxia/iron-responsive transcription and cancer immune evasion." (PMID 41153383, 2025). "STAT3, part of the STAT family, governs cell growth, differentiation, survival, anti-inflammatory activity, tissue repair, and cancer development." (PMID 39808649, 2025). "By interacting with cell surface receptors and then activating the PI3K/AKT, STAT3, and MAPK/ERK pathways, MDK coordinates a series of signaling events that promote cancer cell stemness and cell proliferation." (PMID 40429950, 2025). "Derived from plant-based sources such as green tea, berries, and olive oil, polyphenols have demonstrated the ability to inhibit key cancer hallmarks—including angiogenesis, EMT, and immune evasion—via modulation of NF-κB, STAT3, PI3K/AKT, and MAPK pathways." (PMID 40564985, 2025). "By targeting multiple molecular pathways, including Wnt/β-catenin, PI3K/Akt/mTOR, JAK/STAT3, MAPK, NF-κB, and Notch, curcumin suppresses cancer growth and induces apoptosis." (PMID 41020838, 2025). "The approach adopted in this study is a two-pronged strategy that involves the silencing of both STAT3 and NANOG, which are transcription factors that have been shown to cooperate in the maintenance of cancer cell progression and chemoresistance." (PMID 40729003, 2025). "Oncogenic pathways, including STAT3, ERK1/2, NF-κB, and AKT, have been shown to regulate PD-L1 expression in a variety of cancers." (PMID 40389855, 2025). "The Human Cancer Genome Atlas (TCGA) database was analyzed using the UALCAN GEPIA to investigate the differential expression patterns of SMYD2, STAT3, and EZH2 across various BC subtypes." (PMID 40807332, 2025). "In the constructed pan-cancer drug–gene network, the top hub gene of the network was mTOR, which interacted with 45 drugs, followed by BCL2, STAT3, and EGFR." (PMID 40293950, 2025).
cancer (continued). "Phosphoproteomics has provided detailed maps of phosphorylation sites on STAT3 and STAT5, identifying cancer-specific phosphorylation patterns that contribute to aberrant signaling." (PMID 41463071, 2025). "One such pathway is the signal transducer and activator of transcription 3 (STAT3), which is often hyperactivated in cancer." (PMID 40038745, 2025). "VIRMA not only regulates tumor-associated proliferation and metastasis factors but also participates in the activation of classical oncogenic signaling pathways, such as STAT3 and PI3K/AKT, which are crucial for cancer proliferation and metastasis." (PMID 40723784, 2025). "Numerous studies have indicated that the binding of STAT3 to the HPV16 LCR regulates the expression of viral oncogenes, thereby influencing cancer development." (PMID 40431173, 2025). "Each cancer cell line responds to different AAM-derived factors, but they all funnel through a common JAK2/STAT3 signaling pathway." (PMID 40330466, 2025). "The primary mechanisms include the suppression of cancer cell growth, promotion of apoptosis and infiltration of CD3 and CD8 T cells, and inhibition of the JAK2/STAT3 signaling pathway, and downregulated PD-L1 expression." (PMID 40642092, 2025). "The STAT3 signaling pathway enhances the EMT phenotypes as well as the expression of PD-L1, which is important for cancer metastasis and resistance." (PMID 40389855, 2025). "In this scenario, we reported that the combined inhibition of redox APE1 and STAT3 was more effective in decreasing the migration of MCF‐7 and MDA‐MB‐231 cancer cells compared to individual treatment." (PMID 41090323, 2025). "Cancer-cell factors also condition the nerve microenvironment: the L1 cell adhesion molecule (L1CAM) on PDAC cells induces MMP-2 and MMP-9 via STAT3 signaling, promoting nerve infiltration; L1CAM blockade reduces PNI in mouse models." (PMID 41394398, 2025). "Thus, STAT3 might be a promising target for cancer treatments." (PMID 40061959, 2025). "The levels of p-STAT3 and S100A4 were significantly decreased in RP11-54O7.17 overexpressed cells, whereas carcinoma cell viability and S100A4 expression were dose-dependently reduced after transcription of different concentrations of RP11-54O7.17 in vitro." (PMID 41173847, 2025). "Cancer cells with attenuated proliferation expressing accumulated TLR2 and TRL9 intrabodies demonstrated reduced STAT3 phosphorylation signaling, while apoptotic markers Caspases 3 and 8 were upregulated." (PMID 38390872, 2024). "In EOC, PRL-JAK-STAT pathway signalling can lead to phosphorylation of STAT3 and STAT5, connecting PRL signalling to EMT, EOC cancer stemness and resistance to therapy." (PMID 39285292, 2024). "Mounting research has demonstrated a strong link between the STAT3 signalling cascade and the regulation of matrix metalloproteinase expression and activation, notably MMP‐2, in cancer cells." (PMID 39121240, 2024). "There is an inverse relationship between miR-34a and IL6 levels in various cancers, leading to increased expression of IL6R mRNA and IL6/STAT3 signaling, as observed in OC, colorectal, and pancreatic cancer." (PMID 39766086, 2024). "The studies have confirmed that luteolin can inhibit cancer-cell survival and proliferation, angiogenesis, invasion, metastasis, mTOR/PI3K/Akt, STAT3, Wnt/β-catenin, and cell-cycle arrest, and induce apoptosis." (PMID 38474604, 2024). "STAT3 promotes EMT, a key factor in cancer metastasis, by reducing E-cadherin and increasing vimentin and MMP9 expression." (PMID 39519023, 2024). "In particular, STAT3 and STAT5 are overexpressed or overactivated in several types of cancer and are known to promote cancer progression and malignancy." (PMID 39063337, 2024). "These alternative pathways included c-Myc, WNT, AKT, STAT3 and SMAD3; all of which have important roles in tumourigenesis and cancer progression." (PMID 38195591, 2024).
cancer (continued). "Transcription factors like NF-κB and STAT3, inflammatory enzymes such as COX-2 and MMP-9, and pro-inflammatory cytokines like IL-1, IL-6, IL-8, and TNF-α are crucial in inflammation-induced cancer." (PMID 39061221, 2024). "Tartrate-resistant acid phosphatase (TRAP) staining revealed that the number and size of TRAP+ osteoclasts induced by the conditioned medium from STAT3 inhibition, together with HOXC10-inhibited cancer cells, were significantly deceased." (PMID 39191757, 2024). "Increased CCL2 expression in activated fibroblasts required STAT3 activation by diverse BC-secreted cytokines, and in turn, induced NOTCH1 expression and the CSC features in BC cells, constituting a cancer–stroma–cancer signaling circuit." (PMID 39335478, 2024). "Many studies have demonstrated that IL-6-specific functions in CAFs involve the IL-6/CXCR7 axis and the IL-6/Jak1/STAT3 axis, which play roles in the immune response, EMT and cancer cell migration." (PMID 39075612, 2024). "All reporter activities on LSCs were enhanced by co-culture with PC-3 cancer cells according to the basal values relative to monoculture (ISRE: 32.8, NF-κB: 2.4, STAT3: 2.0, SMAD: 9.5)." (PMID 38467634, 2024). "The binding of angiotensin II to AT1R activates several pathways involved in cancer development, including the PI3K/AKT/mTOR pathway, the RAS/RAF/ERK1/2 pathway, and the JAK/STAT3 pathway." (PMID 39684895, 2024). "As an effective adjuvant therapy for cancer, the core functional components and targets of TCM Bupleurum-Ginger-Licorice formula have been proved to be quercetin and Stat3." (PMID 39173044, 2024). "For instance, cancer cells can induce the generation of iCAFs by releasing IL1β, which activates the LIF/JAK/STAT3 axis and subsequently triggers the expression of IL6." (PMID 38453816, 2024). "Since this regulatory mechanism is frequently disrupted in various cancers, unraveling the processes by which the SHP-1/STAT3 pathway drives metastasis can be essential for improving survival outcomes." (PMID 39664573, 2024). "Silibinin, a major component of milk thistle, has been shown to inhibit PI3K/AKT, STAT3, and TGF-β pathways, reducing cancer cell proliferation and inducing apoptosis." (PMID 39650709, 2024). "IL-6/STAT3 upregulates the expression levels of MMPs including MMP-1, MMP-2, MMP-7, MMP-9 via directly interacting with their promotors in several aggressive cancers." (PMID 38245798, 2024). "Apigenin also inhibits the phosphorylation of JAK2, STAT3, and STAT5, thereby inhibiting the metastasis of cancer cells." (PMID 39458943, 2024). "In cancer stemness research, the JAK/STAT3 signaling pathway is pivotal in linking ncRNA and m6A in tumorigenesis and metastasis." (PMID 39136000, 2024). "JAKs are upstream regulators of signal transducer and activator of transcription 3 (STAT3), which is a well-known oncogenic factor in several human cancers." (PMID 38706884, 2024). "Especially, cucurbitacin I (CuI) has an anticancer effect on several types of cancer cells, including lung cancer, glioma, and breast cancer, via inhibiting the JAK2/STAT3 pathway and suppressing the proliferation of cancer cells in vitro and in vivo." (PMID 38370084, 2024). "Lycorine and lycorine hydrochloride induced apoptosis in cancer cells by regulating multiple intracellular pathways including NF-κB, JAK2/STAT3, and JNK pathways, which are crucial for cancer cell survival and growth." (PMID 39245716, 2024). "Enhanced tyrosine phosphorylation of STAT3 in the presence of USP21 in HAP-1 and A549 cells suggests that USP21-dependent regulation of STAT3 signaling pathway is common for various cancer cells." (PMID 39305962, 2024). "Thus, PRMT5 may maintain STAT3 activation in a variety of cancer types." (PMID 38760429, 2024). "Signal transducer and activator of transcription 3 (STAT3) is a member of STAT family, and can activate its target gene transcription in many cancer cells upon various stimulus inducing the change of cell behaviors." (PMID 38560562, 2024).